S100A8 (S100 calcium binding protein A8)
Diseases named in the same sentence as S100A8 in open-access papers (continued):
Sharing a sentence is not in itself a finding about the gene and the disease.
rheumatoid arthritis (continued). "S100A8/A9 is an excellent biomarker of inflammatory processes, such as rheumatoid arthritis and juvenile idiopathic arthritis." (PMID 26799323, 2016). "Protein S100-A8, is supposed to be involved in the pathology of osteoarthritis, and to have a close relationship with rheumatoid arthritis." (PMID 26438379, 2015). "Calprotectin, a heterodimer of S100A8 and S100A9 subunits, is associated with inflammatory disorders such as rheumatoid arthritis and cystic fibrosis." (PMID 25338166, 2014). "Sera and synovial fluids of patients with rheumatoid arthritis (RA) contain high concentrations of S100A8/A9 that correlate with disease activity." (PMID 23029038, 2012). "High S100A8/9 levels were found in chronically inflamed joints of patients with rheumatoid arthritis." (PMID 22363402, 2012). "Studies have demonstrated that S100A12 and S100A8 are potential biomarker for disease severity and prognosis in some diseases, such as Idiopathic Pulmonary Fibrosis, Rheumatoid Arthritis, Blau syndrome, Chronic Spontaneous Urticaria, active lupus nephritis, and dilated cardiomyopathy." (PMID 40415930, 2025). "S100A8/A9 heterodimer, also known as calprotectin (CP), is a protein complex serving as a biomarker for different inflammatory diseases like inflammatory bowel disease (i.e. Crohn’s disease and ulcerative colitis), and rheumatoid arthritis." (PMID 37467233, 2023). "In rheumatoid arthritis, S100a8/a9 produced by activated macrophages may increase cytokine production via activating the NF-κB and p38 MAPK pathways." (PMID 37396347, 2023). "S100A8/A9 were firstly found in the synovial fluid of rheumatoid arthritis (RA) patients." (PMID 37450409, 2023). "In addition, targeted proteomics revealed that S100A8/A9 is a key plasma biomarker for rheumatoid arthritis." (PMID 35101111, 2022). "S100-A8 and A9 are calcium binding proteins actively secreted by myeloid cells (both neutrophils and monocytes), supposed to play a pivotal role in the pathogenesis of rheumatoid arthritis, inflammatory bowel disease and cystic fibrosis." (PMID 33396627, 2020). "S100A8, S100A9, and S100A12 encode proteins that are well-known markers of acute inflammation and previously implicated in several other inflammatory and autoimmune diseases including systemic lupus erythematosus, rheumatoid arthritis, and atherosclerosis." (PMID 32556497, 2020). "Serum calprotectin is used as a monitoring and pharmacodynamic biomarker for rheumatoid arthritis, and intriguingly S100A8/S100A9 may have further utility in arthritis as a molecular imaging marker of inflammatory activity." (PMID 33228131, 2020). "In that context, neutrophils are able to release S100A8/A9, which are considered as DAMPs and found in large amounts in biological samples from patients with metabolic inflammatory diseases (e.g., gout) and autoimmune diseases (e.g., rheumatoid arthritis, RA)." (PMID 31739406, 2019). "The calgranulins, specifically S100A8 and S100A9, have been implicated in both rheumatoid arthritis and OA and are considered potent damage-associated molecules which exacerbate inflammation following their release under conditions of cellular stress or injury." (PMID 28173838, 2017). "Thus, in rheumatoid arthritis patients the amounts of heterodimer were 1000 fold greater as compared to S100A8 and S100A9 homodimers." (PMID 23626736, 2013). "Protein S100-A9 is highly expressed in the cytoplasm of neutrophils and is found in high levels in extracellular fluids during inflammatory diseases, such as chronic inflammatory bowel disease and rheumatoid arthritis, usually in complex with the related protein S100-A8 (calprotectin)." (PMID 24391738, 2013). "S100A8/9 overexpression was first discovered in cystic fibrosis, but later studies have also demonstrated elevated S100A8/9 levels in active chronic inflammatory bowel disease and in the synovial fluid of patients with rheumatoid arthritis." (PMID 22253789, 2012).
rheumatoid arthritis (continued). "In this sense, S100A8/A9 have been described as being involved in the pathogenesis of chronic inflammatory diseases and more notably in rheumatoid arthritis (RA)." (PMID 31739406, 2019). "Previous studies demonstrated that KYNA reduces TNF-α, S100A12, S100A8/9, and α-defensin production while increasing tumor necrosis factor-stimulated gene-6 protein (TSG-6) levels in rheumatoid arthritis." (PMID 41465233, 2025). "In 2004, Foell and his colleagues found the over-expression of S100 proteins, particularly S100A8, S100A9, and S100A12, at the site of inflammation in Rheumatoid arthritis, chronic inflammatory lung, and bowel disease." (PMID 38956704, 2024). "Calprotectin is a heterodimer formed by two proteins, S100A8 and S100A9, which are the most up-regulated proteins in rheumatoid arthritis." (PMID 37242269, 2023). "Similarly, in rheumatoid arthritis (RA) and psoriatic arthritis serum concentrations of S100A8/S100A9 are related to the inflammatory activity of arthritis, being superior to other biomarkers such as C-reactive protein and erythrocyte sedimentation rate." (PMID 37372165, 2023). "Correlations of a similar magnitude to those found in our study have been described between serum S100A8/A9 and other APPs such as CRP (r = 0.55) in patients with rheumatoid arthritis." (PMID 37627347, 2023). "S100A8 and S100A9 are the most abundant DAMPs in many inflammatory conditions, like infections, auto-immune diseases, rheumatoid arthritis, or inflammatory bowel disease." (PMID 33643287, 2020). "Matrix metalloproteinase (MMP) expression in murine and human chondrocytes was directly stimulated by S100A8 and S100A9, thereby promoting the breakdown of cartilage in osteoarthritis and rheumatoid arthritis." (PMID 31781269, 2019). "S100A8 and S100A9 are considered biomarkers of disease activity in chronic inflammatory pathologies associated with impaired matrix remodeling such as rheumatoid arthritis (RA), inflammatory bowel disease (IBD) and cystic fibrosis." (PMID 30728384, 2019). "It has been longer recognized the relationship between the S100A8/S100A9 expression and inflammatory disorders, including rheumatoid arthritis, inflammatory bowel disease, multiple sclerosis." (PMID 30558666, 2018). "Calprotectin, a heterodimeric complex of S100A8/9 (MRP8/14), has been proposed as an important serum biomarker that reflects disease activity and structural joint damage in rheumatoid arthritis (RA)." (PMID 26373925, 2015). "High concentrations of three of its putative proinflammatory ligands, S100A8/A9 complex (calprotectin), S100A8, and S100A12, are found in rheumatoid arthritis (RA) serum and synovial fluid." (PMID 19284577, 2009). "The expression of S100A8/A9 seems to be tissue and cell specific which is differentially increased in various abnormal conditions such as: Inflammatory Bowel Disease (IBD), Rheumatoid Arthritis (RA), Cystic Fibrosis, different types of cancers and neurodegenerative disorders." (PMID 31622441, 2019). "Nevertheless, low correlations of S100A8/A9 levels in serum with CRP and leukocytes were detectable in patients with tonsillitis which is in concordance with recent findings in patients with myocardial infarction or rheumatoid arthritis." (PMID 29180834, 2017). "It is certain that the content of S100A8, S100A9, and S100A12 proteins in serum or fecal are closely related to diseases and can be used as biomarkers for their detection and diagnosis, including rheumatoid arthritis (RA), inflammatory bowel disease (IBD), cancer, etc.." (PMID 38256103, 2024). "S100A8 and S100A12 are up-regulated in chronic inflammatory conditions, including asthma, rheumatoid, and inflammatory arthritis, perhaps reflecting a more general pathophysiological signal, consistent with increased CAD in disorders such as rheumatoid arthritis." (PMID 21443790, 2011).
rheumatoid arthritis (continued). "Serum and synovial fluid levels of S100A8, S100A9, and S100A8/A9 were all higher in patients with rheumatoid arthritis (RA) than in patients with osteoarthritis (OA), with the S100A8/A9 heterodimer being prevalent." (PMID 16613612, 2006).
atherosclerosis (79 papers, 2006 to 2026). A disease characterized by the build-up of fatty material and calcium deposition in the arterial wall resulting in partial or complete occlusion of the arterial lumen. "Several studies have reported that S100A8/A9 has potential as a predictive biomarker in several inflammation-associated diseases such as rheumatism, inflammatory bowel disease, obesity, and atherosclerosis, among others." (PMID 41601646, 2026). "The atherosclerosis and S100 family signaling-related gene S100A8 showed high diagnostic ability in the GSE121212 (AUC = 0.933), and GSE107361 (AUC = 0.846) datasets between lesional and non-lesional AD." (PMID 39338214, 2024). "S100A8/A9 importance in cardiovascular diseases is underscored by its association with the extent of atherosclerosis in coronary and carotid arteries, plaque vulnerability, and its role in myocardial infarction and myocardial ischemia/reperfusion injury." (PMID 39175627, 2024). "In neutrophils, the increased uptake of glucose uptake via GLUT enhanced glycolysis in these cells, thereby triggering the production of RAGE ligand S100A8/A9, which was linked directly to atherosclerosis through myeloid-specific deletion of Slc2a1 (GLUT1)." (PMID 34178389, 2021). "S100A8 has been linked with other cardiovascular disease such as atherosclerosis and risk for myocardial infarction, stroke, or death." (PMID 26792056, 2016). "At the same time, clinical studies have found that the serum S100A8/A9 level is closely related to the severity of atherosclerosis and the risk of cardiovascular events, which is expected to become a potential biomarker and therapeutic target of atherosclerosis." (PMID 39175627, 2024). "Hence, S100A8/A9 is closely related to atherosclerosis, which is the underlying cause and pathological foundation of MI." (PMID 33282877, 2020). "Previous studies have demonstrated that glycated albumin induces oxidative stress in the vessel wall, enhances pro-inflammatory endothelial response to S100A8/A9, and promotes proliferation and migration of vascular smooth muscle cells, and thereby is associated with accelerated atherosclerosis." (PMID 17178005, 2006). "Given the role of S100A8/A9 in atherosclerosis in both diabetes and obesity-associated myelopoiesis and the subsequent effects of monocytosis on atherosclerosis, targeting S100A8/A9 could be a potential therapeutic target to treat monocytosis and atherosclerosis in metabolic disease." (PMID 31249530, 2019). "While the role of S100A8/A9 in atherosclerosis and HF is increasingly understood, its involvement in cardiac arrhythmogenesis remains poorly understood." (PMID 40948795, 2025). "This preclinical approach underscores the intricate relationship between S100A8/A9 and the pathogenesis of atherosclerosis." (PMID 40948795, 2025). "Summary of key studies on S100A8/A9 contribution to atherosclerosis, heart failure, and cardiac arrhythmias." (PMID 40948795, 2025). "Search terms included “calcium-binding proteins,” “S100A8/A9”, “calprotectin,” combined with “cardiovascular disease,” “atherosclerosis,” “heart failure,” and “arrhythmia” using Boolean operators." (PMID 40948795, 2025). "The temporal dynamics of S100A8/A9 expression throughout disease progression, from subclinical atherosclerosis to plaque rupture or from compensated to decompensated HF, remain poorly described." (PMID 40948795, 2025). "Other scholars explained that S100A8/A9 plays an important role in the early stage of atherosclerosis by promoting leukocyte migration and adhesion to vascular endothelial cells from the perspective of cell migration and adhesion." (PMID 39175627, 2024). "In the future, it is expected to provide a new strategy for early diagnosis and treatment of atherosclerosis through in-depth research on the mechanism of action and clinical application value of S100A8/A9." (PMID 39175627, 2024).
atherosclerosis (continued). "In conclusion, S100A8/A9, as an important inflammatory mediator, plays a variety of roles in the occurrence and development of atherosclerosis." (PMID 39175627, 2024). "Urokinase plasminogen activator-overexpressing macrophages were found to secrete large amounts of S100A8/9, which, in turn, stimulated atherosclerosis and aortic dilation." (PMID 36830768, 2023). "The S100A8/A9 complex is highly expressed in both human and mouse atherosclerotic lesions, and promotes atherosclerosis in diabetic patients." (PMID 37217870, 2023). "Our transcriptome is the first association of AD genomic fingerprinting with the atherosclerosis signaling pathway, which includes genes associated with vascular inflammation (SELE, IL-37, S100A8)." (PMID 26459294, 2015). "The link between S100A8/A9 and atherosclerosis is further supported by clinical studies demonstrating a positive relationship between plasma S100A8/A9 and the severity of coronary artery disease (CAD) in type 1 and type 2 diabetic patients." (PMID 24453429, 2013). "S100A8/A9 amplifies inflammatory processes commonly involved in the pathogenesis of atherosclerosis and autoimmune diseases." (PMID 24453429, 2013). "The pattern of cytokine and S100A9/S100A8 up-regulation characterizes atherosclerosis as a proinflammatory disorder." (PMID 19134193, 2009). "These proteins, along with modular calcium-binding protein 1 (SMOC1), which promotes platelet responsiveness to thrombin, PDGF, which promotes the calcification of vascular smooth muscle cells in atherosclerosis, and neutrophil-derived S100A8/A9, create a proinflammatory, proatherosclerotic milieu." (PMID 40829182, 2025). "Therefore, by promoting cell growth and angiogenesis via RAGE signaling and activation of the mTOR-2, S100A8/A9 promotes intimal hyperplasia, an essential step of atherosclerosis." (PMID 40948795, 2025). "In addition, inhibiting S100A8/A9 or its signal pathway can reduce the progression of atherosclerosis, providing a new idea for the treatment of atherosclerosis." (PMID 39175627, 2024). "Key therapeutic strategies include: RAGE Receptor Antagonists: Agents such as FPS-ZM1 reduce atherosclerosis and inflammatory responses by blocking the binding of S100A8/A9 to RAGE, thereby inhibiting NF-κB and MAPK pathways and reducing inflammatory cell infiltration and plaque formation." (PMID 39175627, 2024). "Additionally, the urokinase plasminogen activator (uPA)/uPA receptor (uPAR)/plasminogen system and the S100A8/A9 complex interact to accelerate the progression of atherosclerosis." (PMID 37217870, 2023). "For instance, some proteins related to atherosclerosis were down-regulated in SF, such as ARG2, CD14, CD44, engulfment, and cell motility protein 1 (ELMO1), neutrophil gelatinase-associated lipocalin (LCN2), MPO, S100A8, or S100A9." (PMID 34572333, 2021). "Hence, these studies linked glucose, glycolysis, S100A8/A9 and RAGE in a cholesterol-independent manner to acceleration of atherosclerosis in mice devoid of Apoe." (PMID 34178389, 2021). "In our analysis, the higher expression of the S100A8 gene in insulin resistance is independent of the WBC profile, but the WBC profile activity and the S100A8/A9-RAGE pathway may be of importance in the etiology of atherosclerosis." (PMID 34886800, 2021). "There are increasing experimental studies and clinical evidence indicating that S100A8/A9 may favor the development of atherosclerosis." (PMID 33282877, 2020). "Moreover, controlling glucose levels in diabetic mice with a sodium glucose co-transporter 2 inhibitor (SGLT2i) reduces circulating S100A8/A9 and prevents both diabetes-induced myelopoiesis and atherosclerosis." (PMID 31249530, 2019). "Interestingly, Atherosclerosis Signaling was the second highest IPA pathway, and includes genes previously associated with vascular inflammation, such as IL-37, SERPINA1, S100A8, selectin E/SELE, lipoprotein lipase/LPL, and MMP1/3/9." (PMID 26459294, 2015).
atherosclerosis (continued). "Treatment with S100A8, a novel adipocytokine associated with visceral fat accumulation and atherosclerosis, did not alter Per1 mRNA level in 3T3-L1 adipocytes." (PMID 25397888, 2014). "The heterodimeric S100A8/S100A9 might therefore play a hitherto unknown role in triggering atherosclerosis in diabetes and renal failure, pathophysiological entities associated with a high AGE burden." (PMID 16573830, 2006). "In addition, increased levels of the serum S100A8 and S100A9 have been reported in diseases such as acute coronary syndrome, coronary artery calcification, cardiovascular intimal hyperplasia, and atherosclerosis, which have a strong association with dyslipidemia." (PMID 40191205, 2025). "One important challenge in using S100A8/A9 as a therapeutic target in chronic wounds is the relative abundance of this protein in human circulation, with median levels of approximately 5 mg/L in healthy individuals and up to 15 mg/L in atherosclerosis patients." (PMID 39337466, 2024). "In addition, S100A8/A9 also plays a role in atherosclerosis by regulating oxidative stress." (PMID 39175627, 2024). "Thus, blocking heterodimeric S100A8/S100A9 might represent a novel therapeutic modality in treating atherosclerosis." (PMID 16573830, 2006). "Indeed, plasma S100A8/S100A9 correlates with leukocyte counts and coronary artery disease (CAD) in type 1 diabetes (T1D), suggesting that targeting of the S100A8/S100A9‐RAGE axis may reduce atherosclerosis and cardiovascular events in diabetic individuals with adequate glycaemic control." (PMID 41489606, 2026). "Myeloid‐restricted Slc2a1 (GLUT1) deletion or pharmacological S100A8/S100A9 inhibition attenuated TIH‐induced myelopoiesis and atherosclerosis." (PMID 41489606, 2026). "In atherosclerosis, CXCL4 drives the differentiation of M4 macrophages, which co-express CD68, MMP7, and S100A8." (PMID 39707183, 2024). "Myeloid‐restricted deletion of Slc2a1 (GLUT1) or pharmacological inhibition of S100A8/S100A9 reduced TIH‐induced myelopoiesis and atherosclerosis." (PMID 37779347, 2023). "Hypothetically, a potential indirect mechanism of S100A8/A9 in NPSLE is through its action on endothelial cells contributing to vasculopathy and atherosclerosis development." (PMID 35804434, 2022). "Three cardiovascular signaling pathways identified by IPA software including “Atherosclerosis Signaling” (related gene: ORM1, ORM2, and S100A8)." (PMID 36277748, 2022). "The S100 proteins S100A8, S100A9, and S100A12 play a crucial role in inflammation and atherosclerosis, while S100A1 plays a role in post-ischemic angiogenesis." (PMID 35203642, 2022). "Previous studies have found that S100A8 and S100A9 are related to obesity, insulin resistance, and atherosclerosis." (PMID 34055926, 2021). "There have been several studies on S100A8/S100A9 expression in neutrophils, endothelial cells, smooth muscle cells, and myocardial cells in the initial development of atherosclerosis, but there are few reports on S100A8/S100A9 expression in EAT." (PMID 31534454, 2019). "Increased plasma levels of S100A8 and S100A9 can serve as marks for human cardiovascular disease, and their deletion protects aganist atherosclerosis to some degree." (PMID 26944061, 2016). "S100A8 and S100A9 in atherosclerotic plaques and calcified stromal vesicles may significantly influence redox- and Ca2+-dependent processes in atherosclerosis and its chronic complications, particularly malnutrition calcification." (PMID 37217870, 2023). "The elevated level of S100A8/9 complex indicates the instability of the atherosclerotic plaque, while the eosinophil cationic protein (ECP) reflects the severity of coronary artery stenosis and predicts the burden of atherosclerosis." (PMID 37217870, 2023).